LINC02512 (long independently transcribed non-coding RNA 2512)
Gene: Long non-coding RNA gene on chromosome 4 (170,343,089 to 170,372,311, forward strand). Ensembl gene ENSG00000251061.
Diseases named in the same sentence as LINC02512 in open-access papers:
LINC02512 is named in the same sentence as 2 diseases in open-access papers, as found by Europe PMC text mining. Sharing a sentence is not in itself a finding about the gene and the disease. The quoted sentences say what the papers report.
tumor (1 paper, 2023). "Sixteen nearby genes showed higher expression in non-cancerous tissues, including seven with almost no expression in tumor (HCN1, SLC22A2, FAM3D, LRFN5, LINC01612, LINC02512, and CNBD1)." (PMID 37509325, 2023).
LINC02512 also shares sentences with these, for which no sentence is quoted: cancer (1 paper).